IL10 (interleukin 10)
Diseases named in the same sentence as IL10 in open-access papers (continued):
Sharing a sentence is not in itself a finding about the gene and the disease.
liver cirrhosis (20 papers, 2013 to 2025). "Similar observations have been made in a model of liver cirrhosis, where macrophages infusion induced an increase of the levels of the anti-inflammatory cytokine IL-10 associated with a reduction of the hepatic myofibroblasts population." (PMID 31827093, 2019). "Single nucleotide polymorphism of TNF-α and IL-10 genes studied in patients with HIV-HCV coinfection with chronic hepatitis or liver cirrhosis." (PMID 23840511, 2013). "In our series, the genotype CA at -592 position of the IL-10 promoter gene was associated with a near significant higher frequency of liver cirrhosis in the bivariant analysis." (PMID 23840511, 2013). "Recent studies have shown that some IL-10 polymorphisms could act as significant biomarkers of liver cirrhosis or HCC." (PMID 38138294, 2023). "Notably, there was also a moderate association between salt intake and the IL-17A–to–IL-10 production ratio, which could be of prognostic relevance in liver cirrhosis according to recent studies." (PMID 40705454, 2025). "Our systematic review and meta-analysis suggest that IL-10 -1082G/A, IL-18 -137G/C, TGF-β1 -509T/C and IFN-γ +874T/A are potentially associated with the risk of liver cirrhosis susceptibility." (PMID 37101651, 2023). "Not only proinflammatory but also anti-inflammatory cytokines, such as IL-10, take part in liver cirrhosis and possibly in HCC development and progression." (PMID 38138294, 2023). "Discussion: This study suggests that IL-10 -1082G/A, IL-18 -137G/C, TGF-β1 -509T/C, and IFN-γ +874T/A were potentially associated with the risk of liver cirrhosis susceptibility." (PMID 37101651, 2023). "The corresponding AUC values for IL-10 and decompensated liver cirrhosis were 0.730 (95% CI 0.589–0.870) and 0.644 (95% CI 0.490–0.798), indicating that these two laboratory parameters have significant value in predicting the progression of DM to DC." (PMID 38115055, 2023). "We found that IL-10 (−1082 GA + AA and AA), IL-18 (−137 GG), TGF-β1 (−509 T) and IFN-γ (+874 T) were potentially associated with the risk of liver cirrhosis susceptibility." (PMID 37101651, 2023). "The previous studies revealed that increased levels of TNF-α as well as IL-2, IL-6, and IL-10 in serum of patients play important roles in the progress of inflammation of severe hepatitis B-related liver cirrhosis." (PMID 27975051, 2016). "Gene polymorphisms of IL-10, IL-18, TGF-β1 have been confirmed to be related to liver cirrhosis by our study, however, it is accepted that IL-1β, IL-28, especially TNF-α plays an important role in the occurrence and development of liver cirrhosis." (PMID 37101651, 2023). "Importantly, inflammation is known to be intimately involved in the progression of both liver cirrhosis and carcinogenesis (e.g., IL-10)." (PMID 32443546, 2020). "Gene polymorphisms of IL-10–1082 GA + AA vs. GG (OR = 1.43, 95% CI = 1.12–1.83), IL-10–1082 AA vs. GG (OR = 2.03, 95% CI = 1.36–3.02), IL-18 -137 GG vs. CC (OR = 3.84, 95% CI = 1.29–11.40), and TGF-β1 -509 T vs. C (OR = 2.52, 95% CI = 1.42–4.48) were significantly associated with liver cirrhosis." (PMID 37101651, 2023). "Elevated concentrations of IL-10 have been related to cytokine patterns favoring the establishment of chronic HCV infection, and experimental models of liver cirrhosis have demonstrated antifibrotic properties of this cytokine." (PMID 39200991, 2024). "Bregs, especially B10 cells, are involved in the process of chronic HBV infection, such as CHB, HBV-related liver cirrhosis, and chronic HBV infection-related renal injury via an IL-10-dependent manner." (PMID 33912178, 2021). "MYC promotes the progression of liver cirrhosis by upregulating the inflammatory factors IL8, IL10, and TGFβ." (PMID 28355233, 2017). "However, pretreatment inhibited the depletion of IL-10 and elevation of TNF-α and IL-6 levels, which shows its anti-inflammatory effect on TAA-induced liver cirrhosis in the rat." (PMID 36458098, 2023).
myocardial ischemia (20 papers, 2011 to 2025). A disorder of cardiac function caused by insufficient blood flow to the muscle tissue of the heart. "In this study, we observed that B cell subsets appeared to modulate the inflammatory milieu in myocardial ischemia through an IL-10–independent mechanism involving cell-cell contact." (PMID 38290007, 2024). "There was a significant decrease in the serum level of the anti-inflammatory cytokine IL-10 due to myocardial ischemia–reperfusion in rats in the CAO group (49.11 ± 8.39 vs. 222.73 ± 26.19 pg/mL in the sham group, p < 0.001)." (PMID 38541636, 2024). "IL-10 is significantly increased in the serum within 6 h following myocardial ischemia/reperfusion injury." (PMID 35743792, 2022). "Here, we provide a novel compound based on the anti-inflammatory properties of IL-10, in which, both in mice and pigs, it has been shown to prevent cardiac necrosis after myocardial ischemia/reperfusion." (PMID 36297479, 2022). "Given the anti-inflammatory role of the cytokine IL-10, we investigated its modulatory effect on the production of oxidized phosphatidylcholines (OxPCs) as well as lipid metabolic responses in global myocardial ischemia/reperfusion (I/R) injury." (PMID 32694752, 2020). "In the blood and the heart, the anti-inflammatory mediator IL-10 was at its highest level 6 and 16 h after priming with 1668-thioate, i.e. at the onset of cardiac ischemia, anti-inflammatory mediators were well above control levels." (PMID 23929312, 2013). "The Decision Tree building with TNF-α, IL-10, and IL-8 is helpful for the diagnosis of blood stasis syndrome in myocardial ischemia animals." (PMID 24371451, 2013). "Taken together, TLR2, TLR9, TNF-α and IL-10 were still elevated above control at the onset of cardiac ischemia." (PMID 23929312, 2013). "Recently, much interest has been focused on the potential role that IL-10 plays a pivotal role in the myocardial ischemia and reperfusion (MI/R)." (PMID 22491677, 2012). "Some inflammatory biomarkers, including IL-10, IL-8, and tumor necrosis factor-1β, might be useful to predict myocardial ischemia–reperfusion injury." (PMID 36747296, 2023). "Taken together, NIL10 may act as an anti-inflammatory effector through the IL-10/STAT3 signaling pathway in myocardial ischemia/reperfusion." (PMID 36297479, 2022). "IL-10 expression was first detected in animal models at 5 h after myocardial ischemia-reperfusion." (PMID 35433880, 2022). "We explored a new pattern of biomarkers for blood stasis syndrome with myocardial ischemia, which was a Decision Tree building with TNF-α, IL-10, and IL-8." (PMID 24371451, 2013). "In addition, it can also promote the secretion of IL-10 and activate the JAK2/STAT3 signaling pathway, showing pharmacological effects in alleviating myocardial ischemia/reperfusion injury." (PMID 39942654, 2025).
autism (19 papers, 2015 to 2025). Persistent deficits in social interaction and communication and interaction as well as a markedly restricted repertoire of activity and interest as well as repetitive patterns of behavior. "Perhaps most significantly, both Long COVID and autism demonstrate concurrent deficiency in interleukin-10, the primary anti-inflammatory cytokine, with reductions of 20% to 40% compared to neurotypical controls." (PMID 40843696, 2025). "The concurrent interleukin-10 deficiency observed in autism patients mirrors the pattern seen in Long COVID, suggesting potential shared mechanisms of inflammatory dysregulation rather than coincidental similarities." (PMID 40843696, 2025). "In the same study, the increased IL-8 was associated with the early onset of autism, while the increased IL-10 and eotaxin levels were correlated with the regressive ASD subtype." (PMID 32992922, 2020). "This was contrary to expectation given studies such as one examining children with 22q11 deletion syndrome (at high risk of autism) that found that level of IL-1β in the blood, and the ratio of IL-6:IL10 in serum was significantly associated with social scores on the ADI-R." (PMID 30498564, 2018). "Importantly, interleukin-10 levels in recovered children typically remain within normal ranges or show compensatory elevation, contrasting sharply with the persistent deficiency observed in both Long COVID and autism." (PMID 40843696, 2025). "They demonstrated that the proinflammatory cytokines IL-12, IL-6, IL-1β and INFγ were significantly increased in patients with severe forms of autism, while the increase in the anti-inflammatory IL-10 was a protective factor against autism." (PMID 36835652, 2023). "In contrast, it was observed that the higher the concentrations of Interleukin 10 (IL-10) and anti-inflammatory agents, the lower the autism symptoms." (PMID 37049390, 2023). "High levels of IL-6 and IL-1β have been also associated with more severe behavioural deficits in children with autism, while high levels of the anti-inflammatory marker IL-10 have been found in individuals with mild autism-related behavioural impairments." (PMID 36451209, 2022). "Further, there is an elevation of some anti-inflammatory cytokines like Interleukin-4 (IL-4) and interleukin-10 (IL-10) in children with autism." (PMID 33269154, 2020). "Research indicates that children with autism exhibit elevated levels of pro-inflammatory cytokines, including interleukin-6 (IL-6) and interleukin-1 beta (IL-1β), alongside reduced levels of anti-inflammatory cytokines, such as interleukin-10 (IL-10)." (PMID 40002751, 2025). "Several reports have also shown decreased IL-10 levels in T cells from children with autism." (PMID 36830973, 2023). "In addition, reports consistently delineate unchanged IL-13, IL-10, IL-5, and IL-4 levels in the plasma/serum and post-stimulated blood immune cells in individuals with autism as compared with controls." (PMID 36268027, 2022). "The reported decrease of IL-10, an anti-inflammatory cytokine, and an increase in IL-12, a pro-inflammatory cytokine, reported in the present study are in support of the evidence that neuronal inflammation is involved in the pathogenesis of autism." (PMID 27824861, 2016). "The convergent cytokine profiles between Long COVID and autism, particularly sustained elevation of IL-6 and TNF-α with concurrent IL-10 deficiency, provide biological plausibility for shared pathogenic mechanisms that could affect neurodevelopment through neuroinflammation." (PMID 40843696, 2025). "Therefore, treatment with 5-AIQ increased expression of IL-10 and could have a potent immunomodulatory potential for the treatment of autism." (PMID 33671196, 2021). "We investigated the influence of 5-AIQ-treatment in BTBR T+ Itpr3tf/J (BTBR) mice as an autism model and used flow cytometry to assess the effect of 5-AIQ on FOXP3, Helios, GATA3, IL-9, IL-10 and IL-17A production by CXCR6+ and CD4+ T cells in the spleen." (PMID 33671196, 2021).
autism (continued). "Regulatory T cells function in children with autism showed a decrease of TGF-β1 levels and a IL-10 production." (PMID 34776843, 2021). "A relevant point to be considered in the neuroimmune interactions occurring in autism is the fact that the intestinal mucosa of children with autism has a higher frequency of TNF-α+ T cells and lower frequency of IL-10+ T cells." (PMID 26441683, 2015).
brucellosis (19 papers, 2007 to 2025). Brucellosis is a bacterial infection that spreads from animals to people via unpasteurized dairy products or by exposure to contaminated animal products or infected animals. "In conclusion, this is the first meta-analysis which investigates the association between IL-10 polymorphism and Brucellosis risk." (PMID 32228609, 2020). "Previous studies have explored the association of IL-10 and IL-6 polymorphisms with Brucellosis risk." (PMID 32228609, 2020). "IL-10 (− 1082 G/A, − 819 C/T, − 592C/A) and IL-6 -174 G/C polymorphisms have a great relationship with IL-10 and IL-6 production, which brings about Brucellosis pathogenesis and development." (PMID 32228609, 2020). "Whereas carrying +874 AA genotype in IFN-γ, producing high/medium IL-10 genotypes, and producing high IL-6 genotype are associated with susceptibility to brucellosis." (PMID 31582997, 2019). "Previous literatures have explored the connection of IL-10 polymorphism with Brucellosis susceptibility." (PMID 31822303, 2019). "For all we know, this research was firstly investigating the connection of IL-10 polymorphisms with Brucellosis risk." (PMID 31822303, 2019). "At present, we conduct the meta-analysis to obtain more accurate results of IL-10 polymorphisms with Brucellosis susceptibility." (PMID 31822303, 2019). "Considerable reports suggested that the promoter polymorphisms of IL-10 are closely related to the output of IL-10 and development and pathogenesis of multiple diseases, including Brucellosis." (PMID 31822303, 2019). "In the present study, we conduct the meta-analysis to get a more precise result of IL-10 polymorphisms with Brucellosis risk." (PMID 31822303, 2019). "In this study, we examined the relationship between brucellosis and cytokine levels, and found IL-4, IL-6, IL-10, IL-17, IFN-γ, and TNF-α were all risk factors for brucellosis, although only IL-6 and INF-γ were independent risk factors for the severity of brucellosis." (PMID 32381058, 2020). "Furthermore, a genetic variant of the IL-10 gene has been reported to influence susceptibility to brucellosis." (PMID 29343543, 2018). "Moreover, IL-10 gene polymorphisms have been associated with increased susceptibility to human brucellosis." (PMID 23818855, 2013). "Furthermore, using cell-specific knock-out mice, we elucidated the immunological mechanisms underlying IL-10 induced immune-regulation during Brucellosis." (PMID 23818855, 2013). "Comparable findings have been reported in human patients with brucellosis, where monocytes exhibited diminished IL-1β, IL-6, and IL-10 secretion in response to LPS stimulation." (PMID 40406273, 2025). "In this study, we showed an increasing frequency of MDSCs in peripheral blood of chronic brucellosis patients, which might be associated with an immunosuppressive status of chronic brucellosis patients, who had the higher level of serum IL-10 and TGF-β compared to healthy individuals." (PMID 38352057, 2024). "After applying Bonferroni correction to adjust for multiple comparisons, levels of TGF-β1 (P = 0.029) in patients with chronic brucellosis and IL-10 (P = 0.033) in patients with acute brucellosis were found to be higher than those in healthy controls." (PMID 34592958, 2021). "We detected a weak positive correlation between levels of TGF-β1 and IL-10 in patients with brucellosis (R = 0.260, P = 0.047)." (PMID 34592958, 2021). "The liver is the most commonly affected organ in patients with active brucellosis, which is why liver macerates from the four experimental groups were collected for evaluation of the expression of the anti-inflammatory genes IL-10 and TGF-β." (PMID 34992597, 2021). "In a murine model of brucellosis, IL-10− knockout mice showed reduced bacterial loads in the spleen, and early IL-10 production by CD4+ CD25+ T cells prevented the immune activation of macrophages and promoted persistent intracellular infection." (PMID 34592958, 2021).
brucellosis (continued). "In our univariate analysis, IL-4, IL-6, IL-10, IL-17, IFN-γ, and TNF-α were risk factors for brucellosis." (PMID 32381058, 2020). "In a murine model, IL-10 has been shown to influence the development of brucellosis by downregulating the response of CD4+ T helper cells and the secretion of IFN-γ." (PMID 29343543, 2018). "Conversely, 3-MA treatment that inhibited autophagy led to elevated expression of TNF-α, IL-6, IL-1β, and IL-10 than those from untreated monocytes from brucellosis patients." (PMID 28659924, 2017). "After intraperitoneal infection, it has been shown that CD4+CD25+ T cells produce IL-10 during acute brucellosis that favor bacterial persistence in mice." (PMID 28018318, 2016). "Reduction in the level of IL-10 indicates an improvement in host resistance mechanism to brucellosis." (PMID 27014640, 2016). "Collectively, this data suggests that macrophage derived IL-10 plays a limited role in development of the chronic disease caused by B. abortus and raises the possibility that T-cells could, indeed, be the main cell type responsible for IL-10 production during early Brucellosis." (PMID 23818855, 2013). "A Th2 response, driven by IL-4 and IL-10, is detrimental to combating brucellosis as it promotes humoral immunity and suppresses macrophage activation." (PMID 24040434, 2013). "Furthermore, in our study, serum IL-10 levels were significantly increased in patients with acute brucellosis, consistent with previous research." (PMID 34592958, 2021). "However, 3-MA treatment restored TNF-α production by M1 macrophages and IL-10 secretion by M2 macrophages in brucellosis patients." (PMID 28659924, 2017). "In addition to this, Brucella change the cytokine level of IFN-γ, TNF-α, IL-10 and TGFβ1 in the early stages of brucellosis in a prpA dependent manner." (PMID 27014640, 2016). "Good candidate vaccines should be able to induce a complex immune response mainly characterized by proinflammatory pattern, cytotoxic CD8+ T-cells and Th1 and Th17 CD4+ T-cells, but also by some anti-inflammatory profile (IL-10), as demonstrated by the proved brucellosis vaccines." (PMID 26352261, 2015). "Indeed, Svetić and collaborators have suggested a possible role for CD4+ T cells in IL-10 production during acute murine Brucellosis." (PMID 23818855, 2013). "And other polymorphisms of IL-10 and IL-6 are not related with Brucellosis susceptibility." (PMID 32228609, 2020). "And neither IL-10-1082 loci nor 592 loci polymorphism is associated with Brucellosis risk." (PMID 31822303, 2019). "We investigated changes in the levels of six cytokines (IL-4, IL-6, IL-10, IL-17, TNF-α, INF-γ) and related clinical biochemical markers in patients with acute and chronic brucellosis in Xinjiang, China." (PMID 32381058, 2020). "We found that IL-4, IL-6, IL-10, IL-17, IFN-γ, and TNF-α levels were higher in those with brucellosis than in controls." (PMID 32381058, 2020). "We found that IL-4, IL-6, IL-10, IL-17, IFN-γ, and TNF-α levels were higher in those with brucellosis than in controls (P < 0.05)." (PMID 32381058, 2020). "We found that IL-4, IL-6, IL-10, IL-17, IFN-γ, and TNF-α levels were higher in patients with brucellosis than healthy controls, indicating a strong immune response was occurring." (PMID 32381058, 2020). "Levels of IL-4, IL-6, IL-10, IL-17, IFN-γ, and TNF-α were all significantly higher in those with brucellosis than in the control group (all P < 0.05)." (PMID 32381058, 2020). "In the early stages of brucellosis, Brucella change the cytokine level of IFN-γ, TNF-α, and IL-10." (PMID 29435171, 2018). "Additionally, the production of IL-1β, IL-6, IL-10, and TNF-α from monocytes in patients with brucellosis was suppressed through the LC3-dependent autophagy pathway during Brucella infection." (PMID 28659924, 2017).